FBXL6 (F-box and leucine rich repeat protein 6)
Description:
Substrate-recognition component of the SCF (SKP1-CUL1-F-box protein)-type E3 ubiquitin ligase complex.
Synonyms: FBL6; FBL6A; PP14630
Tractability: PROTAC: ubiquitination databases record sites on it.
Gene: Protein-coding gene on chromosome 8 (144,355,427 to 144,359,376, reverse strand). Ensembl gene ENSG00000182325.
Subcellular location (Human Protein Atlas): Nucleoplasm; Vesicles
Gene Ontology:
Molecular function: protein binding; ubiquitin-protein transferase activity
Biological process: proteolysis; SCF-dependent proteasomal ubiquitin-dependent protein catabolic process
Cellular component: SCF ubiquitin ligase complex
Genetic constraint (gnomAD): Loss-of-function variants: 49 observed, 47.28 expected, observed/expected ratio (o/e) 1.04, 90% interval 0.82 to 1.32. The synonymous counts are far from expectation, so gnomAD's model fits this gene poorly and the ratio says little. Missense variants: 750 observed, 603.99 expected, observed/expected ratio (o/e) 1.24, 90% interval 1.17 to 1.32. Synonymous variants: 370 observed, 268.3 expected, observed/expected ratio (o/e) 1.38, 90% interval 1.27 to 1.5.
Homologues: Orthologues: chimpanzee FBXL6 (99% identical), macaque FBXL6 (94% identical), guinea pig FBXL6 (81% identical), pig FBXL6 (80% identical), dog FBXL6 (79% identical), mouse Fbxl6 (79% identical), rat Tmem249 (79% identical), tropical clawed frog FBXL6 (30% identical), Drosophila melanogaster CG8272 (19% identical), Drosophila melanogaster CG5003 (17% identical), Caenorhabditis elegans gadr-5 (15% identical), Caenorhabditis elegans zeel-1 (14% identical), and 22 more. Paralogues in human: FBXL7 (18% identical), FBXL13 (17% identical), FBXL2 (16% identical), FBXL20 (16% identical), FBXL18 (16% identical), FBXL4 (16% identical), FBXL5 (14% identical), FBXL16 (14% identical), SKP2 (14% identical), FBXL3 (13% identical), FBXL17 (12% identical), FBXL19 (12% identical), and 3 more.
Diseases named in the same sentence as FBXL6 in open-access papers:
FBXL6 is named in the same sentence as 10 diseases in open-access papers, as found by Europe PMC text mining. Sharing a sentence is not in itself a finding about the gene and the disease. The quoted sentences say what the papers report.
hepatocellular carcinoma (5 papers, 2020 to 2025). A malignant tumor that arises from hepatocytes. "FBXL6 is overexpressed in various cancers and is correlated with the unfavorable prognosis of the disease, such as gastric cancer, colorectal cancer, hepatocellular carcinoma, and renal cell carcinoma, etc.." (PMID 39981438, 2025). "In another study, FBXL6 played an important role in promoting hepatocellular carcinoma owing to the ubiquitination and stabilization of HSP90AA1, which contributed to tumorigenesis in hepatocellular carcinoma." (PMID 36685928, 2022). "Transcriptome RNA-sequencing data of hepatocellular carcinoma (HCC) samples were used to detect the mRNA expression of FBXL6." (PMID 32576198, 2020). "FBXL6 is overexpressed in human hepatocellular carcinoma (HCC), but whether this change drives liver tumorigenesis and lung metastasis in vivo remains unknown." (PMID 37653031, 2023). "The TCGA database showed that FBXL6, an Skp1-Cullin-F box (SCF) E3 ligase, is highly expressed in most human cancers, including liver hepatocellular carcinoma (LIHC), namely, HCC (P < 0.001)." (PMID 38124228, 2023). "This study aimed to investigate whether and how F-box and leucine-rich repeat 6 (FBXL6) regulates KRAS and KRASG12D activity in hepatocellular carcinoma (HCC)." (PMID 38124228, 2023).
liver cancer (3 papers, 2020 to 2023). An epithelial or non-epithelial malignant neoplasm that arises from the liver. "Researchers led by Chuan-Ming Xie from the Southwest Hospital of Army Medical University in Chongqing, China, demonstrated that increased levels of FBXL6 are linked to unfavorable outcomes in liver cancer patients and contribute to the spread of liver tumors in mice." (PMID 37653031, 2023). "However, whether FBXL6 promotes liver cancer metastasis in vivo and the mechanism underlying this action remain unknown." (PMID 37653031, 2023). "Encouragingly, a drug capable of inhibiting TKT effectively blocked FBXL6-driven spread in both human cell cultures and mouse models, offering a promising therapeutic approach for treating advanced liver cancer." (PMID 37653031, 2023). "The activity of FBXL6, a protein involved in cellular clean up mechanisms, is a significant driver of liver cancer growth and spread." (PMID 37653031, 2023). "In supporting with this notion, we found that the c-MYC and FBXL6 mRNAs have a notable correlation in liver cancer samples (R = 0.27, P = 1.3e-0.7)." (PMID 32576198, 2020). "Dual inhibition of MEK and mTOR effectively protects against FBXL6- and KRASG12D-induced tumorigenesis, providing a potential therapeutic strategy to treat this aggressive subtype of liver cancer." (PMID 38124228, 2023). "Taken together, these results indicate that FBXL6 activates the oncogenic KRAS/MEK/ERK axis, promoting mTOR signaling activation, which leads to the carcinogenesis and development of liver cancer." (PMID 38124228, 2023). "Dual inhibition of MEK and mTOR effectively protects against FBXL6- and KRASG12D-triggered hepatocarcinogenesis and lung metastasis, providing a potential strategy to treat this aggressive subtype of liver cancer." (PMID 38124228, 2023). "Here, using an Fbxl6 knock-in mouse model and HCC patient tissues, we demonstrate the crucial roles of FBXL6 in liver cancer development and show by example that blocking TKT would be sufficient to impede HCC development in a subset of HCC patients with high FBXL6 expression." (PMID 37653031, 2023).
colorectal cancer (2 papers, 2025). A primary or metastatic malignant neoplasm that affects the colon or rectum.
gastric cancer (2 papers, 2023 to 2025). A primary or metastatic malignant neoplasm involving the stomach. "Previous studies have revealed that FBXL6 is upregulated in many types of human cancers, such as CRC, renal cell carcinoma, and gastric cancer, and that FBXL6 upregulation contributes to tumorigenesis and cancer development." (PMID 38124228, 2023).
breast carcinoma (1 paper, 2025). "We found that FBXL6 was highly expressed in breast cancer tissues and negatively correlated with prognosis." (PMID 39781342, 2025). "We then downregulated the expression of FBXL6 in breast cancer cells by constructing a siRNA specific to FBXL6 and performed cellular function studies." (PMID 39781342, 2025). "Our research results indicate that FBXL6 is highly expressed in breast cancer and promotes the progression of breast cancer through cell cycle regulation in vivo." (PMID 39781342, 2025). "The downregulation of FBXL6 inhibited proliferation and migration in breast cancer cells." (PMID 39781342, 2025). "Finally, in vitro and in vivo experiments validated the effects of FBXL6 and PDZRN3 on breast cancer development." (PMID 39781342, 2025). "In addition, both in vitro and in vivo experiments have demonstrated that FBXL6 and PDZRN3 can influence the growth of breast cancer cells." (PMID 39781342, 2025).
melanoma (1 paper, 2018). A malignant, usually aggressive tumor composed of atypical, neoplastic melanocytes. "Loss of either CUL3, FBXL6, or RBX1 expression conferred a growth advantage in the presence of vemurafenib, indicating that an unimpaired SCF complex is critical for vemurafenib sensitivity in melanoma." (PMID 29880484, 2018).
tumor (6 papers, 2020 to 2026). "To investigate the molecule mechanism underline the tumor-promoting role of FBXL6, we used the immunoprecipitation/Mass Spectrum (IP/MS) method to identify the interacting proteins of FBXL6." (PMID 32576198, 2020). "In conclusion, our study identifies a superoncogene named FBXL6 that plays a critical role in promoting HCC tumor formation and lung metastasis in mice and humans." (PMID 37653031, 2023). "To systematically identify the substrates of FBXL6, we carried out mass spectrometry-based label-free quantitative proteomics and ubiquitomics on FBXL6-high HCC tumor tissues and adjacent tissues from Fbxl6;Alb-Cre mice." (PMID 37653031, 2023). "Consistently, high coexpression of FBXL6 and p-ERK was associated with a high TNM stage (P < 0.001), tumor size (P = 0.029), vascular thrombosis (P < 0.001), metastasis (P = 0.002) and outcome (P < 0.001)." (PMID 38124228, 2023). "We found that knock out of FBXL6 significantly decreased tumor volume and tumor weight compared with WT cells." (PMID 32576198, 2020). "Down expression of FBXL6 in MDA-MB-231 cells significantly inhibited tumor growth in vivo." (PMID 39781342, 2025). "Although FBXL6 has been proven to have a tumor-promoting effect in several cancers, the mechanisms by which FBXL6 promotes HCC remain unclear, especially in vivo." (PMID 38124228, 2023). "The effect of FBXL6 on HCC tumor growth in vivo was studied in a tumor xenograft model in mice." (PMID 32576198, 2020). "Experiments demonstrated that FBXL6 speeds up the in vitro growth and migration of BLCA cells and contributes to tumor development and metastasis in vivo." (PMID 42091879, 2026). "In line with the in vitro cell assays, we found Prelid2 knockdown markedly decreased the tumor volume and weight of HCC xenograft (P < 0.01), indicating that Fbxl6 elevation synergizes with KrasG12D to drive HCC tumorigenesis via the upregulation of Prelid2." (PMID 38124228, 2023). "Then we can find there are 65 “good genes” among them, and most of 65 “good genes” are negatively correlate with tumor stage, while the only 4 “bad genes” (CDC20, CDCA3, FBXL6, UBE2C) are positively correlate with tumor stage." (PMID 34093816, 2021). "We found that the mRNA levels of some F-box proteins were significantly increased in HCC samples when compared with non-tumor tissues, including FBXL18, FBXL16 and FBXL6." (PMID 32576198, 2020). "Compared with that in normal tissues from Alb-Cre mice (liver-specific Cre recombinase line), the ubiquitination of KRAS at the site lysine 128 (K128) was increased nearly 4.4-fold in LC tumor tissues, suggesting that KRAS ubiquitination may be involved in Fbxl6-mediated hepatocarcinogenesis." (PMID 38124228, 2023). "Moreover, we observed that LSL-KrasG12D/+;Alb-Cre mice developed more severe hepatocarcinogenesis (tumor number, tumor size and the liver/body weight ratio) than LSL-KrasG12D/+;CKO-Fbxl6KO/+;Alb-Cre mice (P < 0.01), suggesting that the knockout of Fbxl6 attenuated KrasG12D-driven HCC tumorigenesis." (PMID 38124228, 2023).
cancer (5 papers, 2014 to 2025). A tumor composed of atypical neoplastic, often pleomorphic cells that invade other tissues. "Meanwhile, considering the high expression rate of FBXL6 in cancer, there is considerable interest in developing therapeutics that target cancers with high FBXL6 expression." (PMID 38124228, 2023). "Likewise, analysis of the RNAseq Expression Public 23Q4 dataset from DepMap, covering approximately 1400 different cancer cell lines, revealed particularly high FBXL6 mRNA expression levels in AML cell lines as compared to other cancer cell lines." (PMID 39014197, 2024). "FBXL6 is highly expressed in HCC as well as other human cancers (P < 0.001)." (PMID 38124228, 2023). "A number of known and previously unknown oncogenes were identified, some of which have already been reported to be associated with cancer, including: ADCY8, ZFAT, BAI1, PTK2, FBXL6, FOXH1, HSF1, and UGT2A1." (PMID 25372838, 2014).
FBXL6 also shares sentences with these, for which no sentence is quoted: renal cell carcinoma (2 papers); bladder cancer (1).